BFSP1 (beaded filament structural protein 1)
Diseases named in the same sentence as BFSP1 in open-access papers:
BFSP1 is named in the same sentence as 26 diseases in open-access papers, as found by Europe PMC text mining. Sharing a sentence is not in itself a finding about the gene and the disease. The quoted sentences say what the papers report.
cataract (9 papers, 2017 to 2025). Partial or complete opacity of the crystalline lens of one or both eyes that decreases visual acuity and eventually results in blindness. "In addition, many cases of pediatric cataracts of dominant or recessive inheritance caused by mutations in BFSP1 have been reported in the scientific literature." (PMID 37511188, 2023). "The abnormal function of BFSP1 may cause diseases, such as cataracts and cortical, juvenile-onset, and nodular basal cell carcinoma." (PMID 28486430, 2017). "In this study, a miRNA-mRNA network was constructed which contains miR-206-3p, miR-493-5p, miR-493-3p, miR-193b-3p, miR-200a-3p, miR-29a-3p, miR-29b-3p, miR-29c-3p, Bfsp1, Plp1, Cnp, Nfasc, Mbp, Pygm, Bfsp2 and Fn1, whose dysregulation may be associated with the cataract pathogenesis." (PMID 37974089, 2023). "Disease gene enrichment analysis demonstrated that the BFSP1 PPI network is significantly associated with Alexander’s disease, cataracts, various eye diseases, and nervous system disorders." (PMID 41470198, 2025). "This role is illustrated by animal studies showing the presence of cataracts in BFSP1 and BFSP2 knock-out mice." (PMID 37511188, 2023). "The importance of BFSP1 and BFSP2 was further evidenced by their mutation‐associated cataract phenotype." (PMID 28177569, 2017). "BFSP1 and BFSP2 have been confirmed to be genes associated with autosomal dominant cataracts." (PMID 37974089, 2023).
hepatocellular carcinoma (3 papers, 2025). A malignant tumor that arises from hepatocytes. "ELISA results showed that TMOD4 also increased the content of BFSP1 in the supernatant of hepatoma cell culture." (PMID 40097750, 2025).
autosomal dominant cataract (2 papers, 2019 to 2023). A syndromic cataract that has autosomal dominant inheritance. "Taken together with previous research, the results of the Family 3 enriched the suspected pathogenicity of the BFSP1 mutation in human autosomal dominant congenital cataract." (PMID 31842807, 2019).
liver cancer (2 papers, 2025). An epithelial or non-epithelial malignant neoplasm that arises from the liver. "Emerging evidence indicates that BFSP1 functions as an independent risk factor and adverse prognostic biomarker in liver cancer." (PMID 41470198, 2025). "It has been found that BFSP1 is an independent risk factor for liver cancer, and its high expression indicates a poor prognosis in patients with liver cancer." (PMID 40097750, 2025). "In addition, BFSP1 is associated with m6A mRNA methylation, which is associated with the survival of liver cancer patients." (PMID 40097750, 2025). "M6-RNA Immunoprecipitation (MeRIP)-qPCR results showed that BFSP1 was significantly enriched at the m6A modification sites in liver cancer cells." (PMID 40097750, 2025). "Here, we found that METTL3 induces aerobic glycolysis in liver cancer by upregulating m6A modification of BFSP1, which can be achieved by recruiting YTHDF1." (PMID 40097750, 2025). "Here, we found that METTL3-mediated BFSP1 mRNA m6A modification enhances BFSP1 stability and promotes aerobic glycolysis and invasion of liver cancer cells." (PMID 40097750, 2025). "The result showed that knockdown of BFSP1 remarkably reduced the level of ECAR and increased the level of OCR in liver cancer cells, whereas overexpression of BFSP1 promoted ECAR level and inhibited OCR level." (PMID 40097750, 2025). "In summary, we found that BFSP1 was upregulated in liver cancer, and BFSP1 and its interacting protein TMOD4 work together to affect the viability, invasion, and aerobic glycolysis of liver cancer cells." (PMID 40097750, 2025). "Nevertheless, this study still provides us with a new perspective to reveal the molecular mechanism of BFSP1 regulating liver cancer progression and metastasis." (PMID 40097750, 2025). "In this study, we comprehensively investigated the functional and clinical significance of BFSP1 in liver cancer and provided direct evidence that BFSP1 upregulation correlates with aggressive tumor biology and poor prognosis." (PMID 41470198, 2025). "Quantitative real-time PCR (QPCR) and Western blotting results showed that BFSP1 was significantly upregulation in liver cancer cell lines." (PMID 40097750, 2025). "Knockdown of BFSP1 inhibited aerobic glycolysis and invasion of liver cancer cells, whereas overexpression of BFSP1 plays the opposite role." (PMID 40097750, 2025). "Research has found that BFSP1, as a poor prognostic marker for liver cancer, is upregulated in liver cancer." (PMID 40097750, 2025). "To explore the effect of BFSP1 on aerobic glycolysis of liver cancer, we transfected sh-BFSP1 and pcDNA-BFSP1 vectors into HepG2 and SNU449 cells." (PMID 40097750, 2025). "Results found that METTL3 was upregulated in tumor tissues and liver cancer cell lines, and it was positively correlated with BFSP1 expression." (PMID 40097750, 2025). "In summary, METTL3-mediated m6A methylation of BFSP1 mRNA plays an important role in the aerobic glycolysis and progression of liver cancer, providing a potential therapeutic strategy for liver cancer." (PMID 40097750, 2025). "It was found that beaded filament structural protein 1 (BFSP1) is a m6A related gene in liver cancer." (PMID 40097750, 2025). "In summary, BFSP1 induces aerobic glycolysis and promotes invasion of liver cancer cells by interacting with TMOD4." (PMID 40097750, 2025). "Here, we found that BFSP1 was upregulated in tumor tissues of liver cancer patients and liver cancer cells." (PMID 40097750, 2025). "Similar to the results of our research, we demonstrated that BFSP1 directly interacts with TMOD4 in liver cancer cells, and knockdown of TMOD4 in vitro reversed BFSP1 overexpression-induced aerobic glycolysis and invasion of liver cancer cell." (PMID 40097750, 2025). "To explore the role of BFSP1 in liver cancer, we first analyzed the expression levels of BFSP1 in liver cancer tissues and cells." (PMID 40097750, 2025).
liver cancer (continued). "Overexpression of BFSP1 promoted the viability, invasion, and aerobic glycolysis of liver cancer cells, whereas knockdown of BFSP1 showed the opposite effects." (PMID 40097750, 2025). "In summary, METTL3 accelerated the malignant progression and lung metastasis of liver cancer by upregulating BFSP1 expression." (PMID 40097750, 2025). "METTL3 knockdown inhibited the expression of BFSP1 mRNA and the m6A level of total RNA in liver cancer cells." (PMID 40097750, 2025). "In this study, our in vivo experiments found that METTL3 induced the growth of mouse liver cancer tumors and induced lung metastasis of tumors by upregulating the m6A methylation level of BFSP1 mRNA, which was similar to the results of previous studies." (PMID 40097750, 2025). "Knockdown of BFSP1 inhibited the vitality of liver cancer cells, whereas overexpression of BFSP1 increased the vitality." (PMID 40097750, 2025). "This study found that METTL3 was upregulated in liver cancer and facilitated the malignant phenotype of cancer cells by promoting m6A methylation of BFSP1 mRNA." (PMID 40097750, 2025). "This study demonstrates the effect of BFSP1 on lung metastasis of liver cancer, and the effect of BFSP1 on the metastasis pathway and mode of liver cancer in vivo needs to be further explored." (PMID 40097750, 2025). "We included 30 patients with liver cancer and detected the mRNA expression of BFSP1 in tumor tissues and adjacent tissues." (PMID 40097750, 2025). "In summary, METTL3 mediated m6A modification of BFSP1 mRNA induced the viability and invasion of liver cancer cells by activating aerobic glycolysis." (PMID 40097750, 2025). "Moreover, knockdown of BFSP1 significantly inhibited the expression of glycolysis-related proteins PKM2, GLUT1, PGK1, and LDHA in liver cancer cells, whereas overexpression of BFSP1 promoted the expression of the glycolysis-related proteins." (PMID 40097750, 2025). "The results showed that overexpression of METTL3 and YTHDF1 promoted the ECAR levels and reduced the OCR levels in liver cancer cells, which could be reversed by knockdown of BFSP1." (PMID 40097750, 2025). "Co-immunoprecipitation, immunofluorescence and GST pull down analyses showed that BFSP1 directly interacted with tropomodalin 4 (TMOD4), and knockdown of TMOD4 reversed BFSP1 overexpression-induced malignant phenotypes and aerobic glycolysis in liver cancer cells." (PMID 40097750, 2025). "Here, we found that BFSP1 was upregulated in liver cancer cells and tissues." (PMID 40097750, 2025). "Then, we explored whether BFSP1 promotes liver cancer cell invasion by inducing aerobic glycolysis in liver cancer cells." (PMID 40097750, 2025). "In this study, we selected BFSP1as the candidate gene, and explored the possible molecular mechanism of m6A-modified BFSP1 in the progression and metastasis of liver cancer in cell models and tumor-bearing mouse model, providing new potential therapeutic targets for liver cancer." (PMID 40097750, 2025). "On the other hand, whether the BFSP1/TMOD4 axis can be used as a clinical indicator of liver cancer needs to be further verified by expanding clinical samples." (PMID 40097750, 2025). "This study expands our understanding of the m6A modification of BFSP1 mRNA in liver cancer, indicating that BFSP1 may have potential values in the treatment of liver cancer." (PMID 40097750, 2025). "We found that BFSP1 was upregulated in liver cancer tissues." (PMID 40097750, 2025). "Here, we mainly explored the mechanism of TMOD4 and BFSP1 in liver cancer." (PMID 40097750, 2025). "Therefore, we speculated that METTL3 may mediate the m6A modification of BFSP1 mRNA and affect aerobic glycolysis in liver cancer by enhancing the stability of BFSP1 mRNA in a YTHDF1 dependent manner." (PMID 40097750, 2025).
liver cancer (continued). "Knockdown of BFSP1 reduced the contents of pyruvate and lactic acid, the activities of HK2, PFK1, and PKM2, as well as the glucose uptake in liver cancer cells, whereas overexpression of BFSP1 plays the opposite role." (PMID 40097750, 2025). "Co-immunoprecipitation (Co-IP) results showed that BFSP1 and TMOD4 were co-precipitated in liver cancer cells." (PMID 40097750, 2025). "The results of transwell showed that overexpression of BFSP1 increased the invasion ability of liver cancer cells by 68%, whereas knockdown of TMOD4 reversed the promotion of overexpression of BFSP1." (PMID 40097750, 2025). "First, although we have confirmed the role of METTL3/BFSP1/TMOD4 axis in the progression and metastasis of liver cancer, since this study is only verified in cell and liver cancer xenograft models, other animal models are needed for further verification." (PMID 40097750, 2025). "In order to explore whether m6A modification occurs in BFSP1 during the progression of liver cancer, SRAMP was used to predict the m6A sites of BFSP1 mRNA, and the results showed that there were multiple m6A modification sites in BFSP1 mRNA." (PMID 40097750, 2025). "Additionally, METTL3 enhances the stability of BFSP1 mRNA in a YTHDF1 dependent manner, thereby promoting aerobic glycolysis in liver cancer cells." (PMID 40097750, 2025). "Moreover, YTHDF1 was upregulated in liver cancer cells, and knockdown of YTHDF1 significantly inhibited the expression of BFSP1." (PMID 40097750, 2025).
Age-related nuclear cataract (1 paper, 2024). A type of age-related cataract that primarily affects the nucleus of the lens. "Variants in many genes underlying inherited forms of cataract (e.g., BFSP1, LIM2, MIP, and CHMP4B) have been shown to exhibit tentative association with age-related nuclear cataract." (PMID 38927721, 2024).
cholangiocarcinoma (1 paper, 2025). A carcinoma that arises from the intrahepatic biliary tree (intrahepatic cholangiocarcinoma) or from the junction, or adjacent to the junction, of the right and left hepatic ducts (hilar cholangiocarcinoma). "BFSP1 mRNA expression was significantly elevated in several malignancies, including LIHC, cholangiocarcinoma, colon adenocarcinoma, esophageal carcinoma, head and neck squamous cell carcinoma, and rectal adenocarcinoma, compared with their corresponding normal tissues." (PMID 41470198, 2025).
nuclear cataract (1 paper, 2024). A cataract (disease) that involves the lens nucleus. "Variants in or near both BFSP1 and BFSP2 have been nominally associated with age-related nuclear cataract in Europeans but only BFSP1 approached genome-wide significance." (PMID 38927721, 2024).
tumor (4 papers, 2021 to 2025). "Moreover, the observed associations between BFSP1 and TIICs highlight the critical role of the tumor immune microenvironment in influencing LIHC outcomes and therapeutic responses." (PMID 41470198, 2025). "Furthermore, BFSP1 expression was correlated with promoter hypomethylation and associated with patterns of tumor-infiltrating immune cells, including specific immune cell subtypes such as M1 and M2 macrophages." (PMID 41470198, 2025). "Furthermore, BFSP1 has been implicated in epigenetic and post-transcriptional regulatory mechanisms, including N6-methyladenosine mRNA methylation, which is closely associated with patient survival and tumor progression in LIHC." (PMID 41470198, 2025). "These distinct co-expression and interaction networks provide mechanistic insights into the multifaceted roles of BFSP1 in LIHC tumor biology." (PMID 41470198, 2025). "The results showed that METTL3 overexpression promoted the expression of BFSP1, METTL3, and TMOD4 in mouse tumor tissues, whereas sh-BFSP1 reversed the effect." (PMID 40097750, 2025). "In vivo experiments in mice confirmed that METTL3 increased BFSP1 stability by promoting m6A modification of BFSP1 mRNA, and knockdown of BFSP1 inhibited tumor growth and metastasis." (PMID 40097750, 2025). "After overexpression of METTL3, mice showed faster tumor growth (tumor volume increased by 96% and tumor weight increased by 2.12 times at 30 days), which was reversed by sh-BFSP1." (PMID 40097750, 2025). "Specifically, genomic changes in BFSP1 (such as CNVs) may influence the overall composition of the tumor immune microenvironment, thereby affecting immune surveillance and tumor progression." (PMID 41470198, 2025). "The results showed that BFSP1 was upregulated in tumor tissues." (PMID 40097750, 2025). "In the present study, we identified five genes (LDHA, PPAT, BFSP1, NR0B1, and PFKFB4) associated with the tumour immune microenvironment in HCC patient cohorts that may be applied as potential biomarkers of HCC immunotherapy outcome." (PMID 33407546, 2021). "Because the data are observational, causal relationships cannot be firmly determined, and revers causality cannot be fully excluded—advanced tumor characteristics or subsequent treatment may affect BFSP1 expression rather than BSFP1 influencing disease progression." (PMID 41470198, 2025). "We identified BFSP1 as a multifaceted biomarker in LIHC, impacting tumor progression, immune microenvironment, and therapeutic response." (PMID 41470198, 2025).
cancer (2 papers, 2025). A tumor composed of atypical neoplastic, often pleomorphic cells that invade other tissues. "The consistent overexpression observed across independent datasets supports the potential of BFSP1 as a pan-cancer biomarker and its diagnostic and prognostic relevance in LIHC." (PMID 41470198, 2025). "BFSP1, an m6A RNA methylation-associated gene in cancer, is closely related to carbohydrate catabolism and glycolysis." (PMID 40097750, 2025). "To further evaluate the regulatory mechanisms underlying BFSP1 expression across cancer types, we systematically examined the correlation between CNVs, DNA methylation, and BFSP1 mRNA levels." (PMID 41470198, 2025). "Moreover, pan-cancer analysis demonstrated that increased BFSP1 expression was consistently associated with adverse survival outcomes across multiple cancer types." (PMID 41470198, 2025). "BFSP1 has traditionally been regarded as a lens-specific structural protein; however, recent pan-cancer analyses have revealed its aberrant expression in several malignancies, including LIHC." (PMID 41470198, 2025). "CNV analysis revealed a positive correlation between BFSP1 mRNA expression and multiple cancers, including LIHC." (PMID 41470198, 2025). "The results revealed significant hypomethylation of the BFSP1 promoter region in several cancer types, including LIHC." (PMID 41470198, 2025). "Although traditionally considered as an eye lens-specific cytoskeletal protein, recent pan-cancer analyses have identified aberrant expression of BFSP1 in various malignancies, including LIHC, suggesting its role in oncogenic processes beyond ocular tissues." (PMID 41470198, 2025). "Additionally, BFSP1 may be involved in carbohydrate metabolic pathways, highlighting its pleiotropic role in cancer biology." (PMID 41470198, 2025). "Similar patterns of positive and negative correlations between BFSP1 expression and immune cell infiltration have been observed across multiple other cancer types." (PMID 41470198, 2025). "Conversely, DNA methylation demonstrated a strong negative correlation with BFSP1 mRNA expression in several cancer types, including LIHC." (PMID 41470198, 2025).
infection (1 paper, 2024). The state of being infected such as from the introduction of a foreign agent such as serum, vaccine, antigenic substance or organism. "Furthermore, proteins related to the cytoskeleton and cytoskeleton remodeling (KRT2 and PLXNA4) and genes coding for components of the cytoskeleton, KRT13 (LOC100515166), KRT17 (LOC100737113), KRT6A, and BFSP1, were significantly higher expressed after infection with swH1N1 compared to huH1N1." (PMID 39247193, 2024).
BFSP1 also shares sentences with these, for which no sentence is quoted: Alexander disease (1 paper); cervical squamous cell carcinoma (1); colon adenocarcinoma (1); congenital cataracts (1); endocervical adenocarcinoma (1); esophageal carcinoma (1); glioblastoma multiforme (1); head and neck squamous cell carcinoma (1); kidney chromophobe (1); lung adenocarcinoma (1); nervous system disorder (1); nodular basal cell carcinoma (1); rectal adenocarcinoma (1); renal clear cell carcinoma (1); thyroid carcinoma (1); uterine corpus endometrial carcinoma (1).